PRELP (proline and arginine rich end leucine rich repeat protein)
Diseases named in the same sentence as PRELP in open-access papers (continued):
Sharing a sentence is not in itself a finding about the gene and the disease.
tumor (continued). "LUM, COL18A1, BGN, PRELP, and ASPN showed increased expression in tumor tissue compared to the paired NAT tissue, inconsistent with the declined trend in other histologic subtypes." (PMID 39305996, 2024). "The presence of transcripts for FMOD, PRELP and OMD was widespread in the patients analyzed, while expression of LUM and KERA was detected in only around 50% of cases in both healthy and tumor tissue." (PMID 34440771, 2021). "In the gene set developed by applyingthe BVS procedure on the normal tissue dataset, a high expression ofPPP2R4, PRELP, CALLA,ISG20L2 was predictive of tumour capsular penetration." (PMID 21479216, 2011). "Transcripts for the five genes encoding class II SLRPs (FMOD, LUM, PRELP, KERA and OMD) were quantified in both healthy and tumor tissue, with no significant expression differences between tissue type." (PMID 34440771, 2021). "When we combined the data for OMD and PRELP, the expression of both genes below the cutoff value was found only in tumor samples and in none of the normal tissues (specificity 100%)." (PMID 33202923, 2020). "PRELP was expressed in tumor cells of some MCL patients (3/5) but not in FL (0/2), T- or B-PLL (0/6), HCL (0/2), MM (0/6), CML (0/5), AML (0/5), and ALL (0/10)." (PMID 23826326, 2013). "PRELP has been shown to affect the immunogenicity of tumors by upregulating MHC class I surface expression and activating IFN signaling, which could modulate tumor development as well as the TME leading to an enhanced CD8+ T cell infiltration." (PMID 37730606, 2023). "In LSCCs, three significant expression alterations that were not detectable in RSCCs were observed specifically PRELP, CHAD and PODN, all of which underwent downregulation in the tumor tissues." (PMID 34440771, 2021). "Strong polyclonal activation (PMA/ionomycin) of normal B and T lymphocytes did not induce PRELP expression (data not shown), suggesting that the expression in CLL might reflect a constitutive tumor-related aberration in vivo." (PMID 23826326, 2013).
cancer (15 papers, 2018 to 2025). A tumor composed of atypical neoplastic, often pleomorphic cells that invade other tissues. "Notably, 29 genes, including APOBEC2, GDNF, and PRELP, have been confirmed by existing literature to be associated with cancer development and progression." (PMID 39968416, 2025). "Generally, PRELP transcription was diminished in HCCs and may be associated with cancer progression." (PMID 33033521, 2020). "Functional difference between OMD and PRELP may be associated with certain cancer phenotypes." (PMID 33202923, 2020). "PRELP treatment has been shown to suppress cancer progression by inhibiting the TGF-β and EGF pathways leading to the control of the EMT." (PMID 37730606, 2023). "Next to its therapeutic potential, our bioinformatics pan-cancer analysis as well as our functional results demonstrated the potential use of PRELP as prognostic and therapeutic markers." (PMID 37730606, 2023). "To estimate the contribution of PRELP downregulation in human cancer, we biostatistically compared expression profiling data of PRELP−/− mouse retina with publicly available data using the Analysis Match function of IPA software (QIAGEN)." (PMID 36230849, 2022). "mRNA expression profiling of PRELP−/− mouse retina and PRELP-treated RB cells found that PRELP contributes to RB progression via regulation of the cancer microenvironment, in which loss of PRELP reduces cell–cell adhesion and facilitates EMT." (PMID 36230849, 2022). "We previously showed that PRELP gene overexpression inhibits cancer progression by blocking TGF-β and EGF pathways, reversing EMT, activating cell adhesion, and inhibiting various oncogenic pathways." (PMID 36371227, 2022). "This can have a profound effect on cancer-specific mechanisms, Recently, we reported that PRELP expression was profoundly suppressed in the majority of epithelial cancers." (PMID 36230849, 2022). "Analysis of the ONCOMINE database showed that gene expression of PRELP is suppressed in many types of cancer." (PMID 33428936, 2021). "Our data indicate that OMD and PRELP are endogenous inhibitors of cancer initiation and progression by controlling EMT." (PMID 33202923, 2020). "This study demonstrates that the functions of OMD and PRELP are partially redundant in the regulation of both cell–cell integrity and cancer initiation/progression, and they are potentially important, especially for bladder cell therapeutics." (PMID 33202923, 2020). "The expression of both OMD and PRELP in tumors was drastically lower compared to normal tissues and declined progressively with cancer stage." (PMID 33202923, 2020). "This potentially means that it is possible to classify a patient’s clinical state based solely on their OMD and PRELP expression status from early-stage cancers." (PMID 33202923, 2020). "The downregulation of OMD and PRELP expression was observed in all of the cancers we analyzed, including bladder cancer." (PMID 33202923, 2020). "To further assess the role of OMD and PRELP in cancer, we overexpressed or underexpressed the two proteins in cultured cells and performed gene expression analysis using microarrays (Affimetrix GeneChip® System)." (PMID 33202923, 2020). "Notably, MONet identified 37 novel driver genes that were missed by other methods, including 29 genes such as APOBEC2, GDNF, and PRELP, which are corroborated by existing literature, underscoring their critical roles in cancer development and progression." (PMID 39968416, 2025). "In addition, compounds should be identified, which upregulate PRELP expression leading to anti-cancer activity." (PMID 37730606, 2023). "Additionally, the PRELP gene is located on chromosome 1q31.1, which is a site frequently perturbed in cancer." (PMID 36230849, 2022). "In contrast, PRELP was observed to be reduced in other cancers." (PMID 35202840, 2022). "PRELP-mediated improvement of the cancer microenvironment might be a better strategy for treatment of RB." (PMID 36230849, 2022).
cancer (continued). "Elucidating the roles of PRELP in cancer may help understand the clinical significance of the classified genes identified by machine learning algorithms." (PMID 36556220, 2022). "Studies of PRELP in human cancers have been reported previously." (PMID 33033521, 2020). "For many genes, their function in cancer is still unknown while some others have already been implicated in cancer such as: RABIF, KLHL12, ADIPOR1, CYBR5R1 and PRELP." (PMID 29844869, 2018). "Thus, double knockout of OMD/PRELP and E-cadherin may reveal the process of malignant cancer initiation." (PMID 33202923, 2020). "Our ECM panel for PCC-NOS includes SLRPs like LUM, BGN, PRELP, and ASPN, which exhibit dual functions in cancer." (PMID 39305996, 2024). "PRELP can inhibit TGF-β and enhance cell-cell adhesion, thereby effectively hindering the progression of cancer." (PMID 39507711, 2024). "Furthermore, differentially quantified proteins (such as PGS2, UGDH, ASPN, LUM, COEA1, and PRELP) were found in comparisons of healthy and cancer breast tissues, suggesting potential utility of the All-in-One pipeline for the emerging application of proteomic cancer sub-typing." (PMID 36937585, 2023). "Although we analyzed pathways at the induction of PRELP expression, specifically in OCCC, there have been some studies reporting PRELP in other cancer types." (PMID 36556220, 2022). "Therefore, PRELP may have potential as an anti-cancer drug to treat RB patient in the future." (PMID 36230849, 2022). "We also confirmed low expression of PRELP in RB cell lines of Y79 and WERI-RB1 as observed in other cancer cell lines." (PMID 36230849, 2022). "ECM proteins, including PRELP are important in regulating ocular tissues This paper and our previous paper propose that PRELP is an important ECM protein in the initiation and progression of various cancers through control of cell–cell." (PMID 36230849, 2022). "In addition, expression profiling analysis of PRELP−/− mouse retina indicated that PRELP itself has ability to regulate cancer-related pathways, cell adhesion, and EMT without RB1 abnormality." (PMID 36230849, 2022). "Although cell of origin is important for understanding RB, understanding of the autonomous PRELP suppression mechanisms may not be very important because PRELP is a secreted protein and influences cancer progression via microenvironment." (PMID 36230849, 2022). "Using the Functional Analysis mode, “molecular mechanism of cancer” was identified as one of the most significantly affected biological functions and/or diseases in all four conditions of OMD overexpression, OMD depletion, PRELP overexpression, and PRELP depletion." (PMID 33202923, 2020). "Thus, PRELP may regulate a set of genes related to the PI3K-AKT signaling pathway regardless of carcinoma type to some extent." (PMID 36556220, 2022). "Moreover, the molecular function of PRELP as a regulator of major cancer-related pathways of TGF-β, EGF, and Wnt also strongly indicates that PRELP suppression is not just consequence of RB development." (PMID 36230849, 2022).
cardiovascular disease (1 paper, 2022). "Overall, previous studies have elucidated the pathological roles or diagnostic values of NPPA, OMD, and PRELP in different cardiovascular diseases, but have not yet involved DCM with HF." (PMID 36544902, 2022).
hematological malignancies (1 paper, 2013). "Next, we tested PRELP mRNA expression in other hematological malignancies." (PMID 23826326, 2013).
infection (1 paper, 2020). The state of being infected such as from the introduction of a foreign agent such as serum, vaccine, antigenic substance or organism. "Referring to foregoing results, we then ectopically overexpressed PRELP in HCCLM3 cells and knocked down PRELP in SMMC-7721 cells through lentiviruses infection." (PMID 33033521, 2020).
PRELP also shares sentences with these, for which no sentence is quoted: acute myocardial infarction (1 paper); biliary atresia (1); colorectal tumors (1); dementia (1); Duchenne muscular dystrophy (1); endometrial cancer (1); heart disease (1); Hypertension (1); insomnia (1); liver (1); lymph node metastasis (1); Myocardial fibrosis (1); osteoarthritis (1); ovarian clear cell cancer (1); psoriasis (1); skin cutaneous melanoma (1); T-cell leukemia (1); urothelial carcinoma (1).